BRAF (B-Raf proto-oncogene, serine/threonine kinase)
Diseases named in the same sentence as BRAF in open-access papers (continued):
Sharing a sentence is not in itself a finding about the gene and the disease.
melanoma (continued). "BRAF and MEK inhibitors in patients with BRAF-mutated melanoma have even higher overall response rates (70%), but fewer durable responses due to the development of resistance." (PMID 32392717, 2020). "As an example, while very effective to treat BRAF mutant melanomas, BRAF inhibitors showed poor responses in colon cancers harboring the same oncogenic mutation." (PMID 33291749, 2020). "First, we investigated a relatively large number of acral melanoma using immunohistochemical analysis and found that intratumor BRAF V600E heterogeneity was observed in more than half of BRAF V600E-positive melanomas (52.4%, 11/21)." (PMID 32143442, 2020). "Third, the possible effects of BRAF mutation on the miR-335/ROCK1 axis need further illumination due to the frequent BRAF V600E in melanoma." (PMID 32219065, 2020). "Cancer-associated fibroblasts induce phenotypic switching of melanoma cells into a mesenchymal-like phenotype and activate PI3K signaling to confer resistance to BRAF inhibitors." (PMID 32626712, 2020). "We also confirmed that ~63% of progressed samples, from BRAF-mutant melanoma patients who experienced disease progression following BRAFi or BRAFi + MEKi therapy, showed significantly reduced HAT1 expression levels compared with matched pre-treatment samples." (PMID 32371878, 2020). "In this study, we examined the role of p38, JNK and NF-κB pathways in PMCA4b regulation, as all have been found activated in BRAF mutant melanomas." (PMID 32414111, 2020). "NRP1 was previously shown to mediate EGFR upregulation, driving resistance to targeted therapies, such as those inhibiting BRAF in melanoma cells." (PMID 32784465, 2020). "Treatment of melanoma cells with the GLS inhibitor BPTES enhanced the anti-tumour activity of BRAF inhibition by suppressing the switch toward glutamine metabolism and OXPHOS." (PMID 33092283, 2020). "Silencing of PGC1α suppressed the oxidative phenotype and enhanced cell killing of melanoma cells following BRAF-inhibitor treatment in vitro and in vivo." (PMID 32258244, 2020). "The discovery of BRAFV600E mutations in a wide spectrum of gliomas has led to optimism that these tumors can be therapeutically targeted by potent inhibitors of the mutant form of BRAF developed for the treatment of melanoma." (PMID 32523649, 2020). "This combination rendered tumors more sensitive to ICB, and adding PD-1 blockade further potentiated BRAF/MEKi in a mouse model of melanoma, and has been translated to the clinic for patients with mutant BRAF." (PMID 33597954, 2020). "A similar finding has been reported with resistance to BRAF inhibitors in NF1-mutant and BRAF-mutant melanomas, yet the tumors were sensitive to combined inhibition of MEK and mTOR." (PMID 31906320, 2020). "Here, we show that dietary glutamine supplementation significantly inhibits melanoma tumour growth, prolongs survival in a transgenic melanoma mouse model, and increases sensitivity to a BRAF inhibitor." (PMID 32620791, 2020). "Previously, our laboratory identified PMCA4b as a putative metastasis suppressor in BRAF mutant melanoma cells where PMCA4b expression is down-regulated." (PMID 32414111, 2020). "This study also illustrates that SBRT + IL-2 has activity in patients after progression on IL-2 monotherapy, CPI or BRAF-targeted therapy, the latter of which are the current standards of care for patients with advanced melanoma." (PMID 32467299, 2020). "miR-204-5p and miR-211-5p have high expression levels in A375 melanoma cells resistant to the B-Raf Proto-Oncogene, Serine/Threonine Kinase (BRAF) inhibitor vemurafenib, compared to parental cells." (PMID 33348804, 2020).
melanoma (continued). "We show that BRAF-mutant melanoma cells with acquired resistance to BRAF inhibition have a heterogeneous metabolic profile that is characterised by an overall lower glycolytic, bioenergetic and phospholipid metabolic activity compared to sensitive cells." (PMID 31819183, 2020). "Fifth, in BRAF-mutant models, BRAF inhibitors activated the mitogen-activated protein kinase (MAPK) pathway in macrophages which then produced VEGF to promote melanoma tumor growth." (PMID 32509781, 2020). "Histological examination of melanoma sample from vemurafenib-resistant patients confirmed increased fibroblastic stroma and stiffer matrix once resistance to BRAF inhibitors had developed." (PMID 33212834, 2020). "Adjuvant therapy for melanoma has radically changed over the past few years—anti-PD-1 or BRAF-directed therapy is the new standard of care." (PMID 32708268, 2020). "The discovery of activating BRAF mutations in half of all melanomas has led to the development of molecularly targeted therapy with BRAF and MEK inhibitors, which dramatically improved outcomes of patients with stage IV BRAF-mutant melanoma." (PMID 32695793, 2020). "BRAF inhibitors, such as vemurafenib, have shown efficacy in BRAF-mutant melanoma treatment but acquired-resistance invariably develops." (PMID 31819183, 2020). "Aside from BRAF mutations, NRAS mutations have also been described in about 15% of melanoma patients, and result in the reduction of the intrinsic GTPase activity and in the constitutive activation of NRAS." (PMID 32393282, 2020). "BRAF inhibitors are effective for BRAF V600E-mutant tumors and are in clinical use for the treatment of melanoma and a subset of lung cancer." (PMID 33060766, 2020). "Mutations in the promoter region of the telomerase reverse transcriptase gene (TERTprom), along with mutations in BRAF/NRAS, are the most frequent genetic alterations detected in melanoma." (PMID 32290374, 2020). "Sweetlove and co-workers presented in a short-term experiment that the selumetinib and BEZ235 combination has nearly additive effect on most BRAF mutant melanoma cell lines, similar to our long-term assay results." (PMID 33081092, 2020). "To identify candidate therapeutic targets for BRAF inhibitor resistant melanoma, we conduct CRISPR screens in melanoma cells harboring an activating BRAF mutation that had also acquired resistance to BRAF inhibitors." (PMID 32413516, 2020). "An in vitro study demonstrated that compared with wild-type BRAF melanoma cells, mutant BRAF melanoma cells showed stronger PTS activity and were more sensitive to PTS-targeted cytotoxic drugs." (PMID 33292222, 2020). "An implementation study employing a customized Ampliseq NGS panel including 35 genes reported BRAF, TERT and NRAS as the most prevalent mutated genes in a set of 100 primary melanoma samples." (PMID 33083132, 2020). "Vemurafenib is a potent RAF kinase inhibitor with remarkable clinical activity against BRAF (V600E) melanoma." (PMID 32900991, 2020). "They shut down signaling through extracellular signal-regulated kinase (ERK) and, consequently, inhibit cellular growth in BRAF-mutant melanoma cells and induce tumor regression in xenograft models." (PMID 33036192, 2020). "miR-524-5p suppresses MAPK/ERK pathway-triggered melanoma cell proliferation by directly binding to the 3’-UTR of both BRAF and ERK2." (PMID 32604720, 2020). "In BRAF WT melanoma, few data have been published to date about the combination of MEKi with anti-PD1." (PMID 32585901, 2020). "Many of these genes, including Phgdh, Psat1, and Psph, play important roles in serine biosynthesis, a process that has been shown to accelerate melanoma progression and confer resistance of BRAF V600E mutant melanoma to the targeted inhibitor vemurafenib." (PMID 32175283, 2020).
melanoma (continued). "Usually, PIK3CA activating mutations are rare in melanoma with a frequency of 5%, despite the ability of activated PIK3CA (H1047R) to cooperate with BRAF V600E promoting melanomagenesis in mouse models." (PMID 32850962, 2020). "In summary, we found that the activation of Galectin-1/NRP1 autocrine signaling is a new mechanism conferring independence from BRAF kinase activity to oncogene-addicted melanoma cells." (PMID 32784465, 2020). "The COX2 selective inhibitor celecoxib alone and in combination with BRAF/MEKi has shown tumor inhibitory effects in preclinical melanoma studies." (PMID 32967672, 2020). "Therapy in melanoma has made great progress with the advancement in receptor tyrosine kinase (RTK) inhibitors targeting BRAF/MEK1/2 and immunotherapies." (PMID 33392197, 2020). "A phase II trial (NCT02159066) evaluating the use of third agent in encorafenib + binimetinib therapy in stage III-IV metastatic BRAF V600 melanoma." (PMID 32092958, 2020). "Melanomas with NF1 mutations typically occur on chronically sun-exposed skin or in older individuals, show a high mutation burden, and are wild-type for BRAF and NRAS." (PMID 32393282, 2020). "These regulators have the potential to be used to treat all subtypes of melanoma because many of the dependencies extend beyond the BRAF-mutant subtype of melanoma." (PMID 33024276, 2020). "Preclinical studies have investigated the encapsulation of MEK inhibitors in pegylated nanoliposomes for oral administration, or the topical administration of BRAF inhibitor-loaded nanovehicles into melanoma lesions using a microneedling technique." (PMID 33003483, 2020). "This cocktail is commonly used for melanoma treatment but has also been assessed in BRAF-mutant cancers and is expected to provide new therapeutic options in BRAF-mutated MBC." (PMID 33276556, 2020). "Using CRISPR-Cas9 technology, we recently showed that BRAF-mutant melanoma cells devoid of MNK1 were less metastatic in an experimental model of lung metastasis." (PMID 32517051, 2020). "Accordingly, we generated three different BRAF-mutant human melanoma clones with acquired resistance to vemurafenib and investigated differences in their metabolic characteristics and dependencies." (PMID 31819183, 2020). "Our study indicates that the CAP and SN combination dysregulated autophagy-related genes, including TFEB and ZKSCAN3, which have important functions in connecting BRAF signaling to autophagy-lysosome-mediated catabolism in melanoma." (PMID 32178401, 2020). "Recently, several reports have linked resistance to serine/threonine protein kinase BRAF (BRAF) inhibitors with augmented glutamine dependency, suggesting that altered glutamate-dependent anabolic pathways may be central to acquiring drug resistance in cancers including melanoma." (PMID 32937954, 2020). "Transcriptional and immunological context has also been confirmed as a key determinant of efficacy for BRAF inhibition in BRAF mutant melanoma." (PMID 32922659, 2020). "BRAF, NRAS, and KIT are three well-known genes associated with melanoma, and BRCA1 and BRCA2 are two representative genes associated with breast cancer." (PMID 33121438, 2020). "Examples include EGFR and ALK inhibitors in non-small cell lung cancer, BRAF inhibitors in melanoma, HER2-targeting agents in breast cancer, and immune checkpoint inhibitors of CTLA4 or PDL1 in melanoma or non-small cell lung cancer 6-10." (PMID 31903155, 2020). "Overall responses from patients with metastatic BRAF mutant melanoma are better with therapies combining BRAF and mitogen-activated protein kinase kinase (MEK) inhibitors." (PMID 32466585, 2020). "To further test the most interesting predictions from the MOP solution, we experimentally validated in-house two Pareto optimal drug triplets and their subcombinations in the BRAF-V600E melanoma cell line MALME-3M." (PMID 33370253, 2020).
melanoma (continued). "To date, studies on melanoma cell metabolism under targeted therapies or after resistance acquisition mainly focused on cells treated with BRAF inhibitors." (PMID 32455924, 2020). "In this study, patients with BRAF‐mutant advanced melanoma who received treatment in the USON had demographic and clinical characteristics similar to those reported by similar studies performed in the community oncology setting." (PMID 32871054, 2020). "Here, we tested the role of BRD/BET proteins in the upregulation of RTKs and resistance to BRAFi/MEKi therapy in BRAF V600E melanoma models." (PMID 31932756, 2020). "Here, using as working models BRAF-mutant melanoma cells we have demonstrated for the first time that the RT inhibitor SPV122 strongly synergizes with MAPKi to reduce cell proliferation, induce apoptosis and delay drug resistance in vitro." (PMID 32933538, 2020). "Intriguingly, melanoma bone lesions have significantly lower response to BRAF or MEK inhibitor therapies." (PMID 31323160, 2020). "We identify the JUN family transcription factors and the ETS family transcription factor ETV5 as key regulators of CDK6, which together enable resistance to BRAF inhibitors in melanoma cells." (PMID 32413516, 2020). "This is shown by the development of OXPHOS dependency with acquired resistance to BRAF inhibitors upon treatment in BRAF-mutant melanoma." (PMID 33092283, 2020). "We describe a novel correlation between the Cav3.1 isoform and the increased basal autophagy in BRAFV600E-mutant melanomas and after acquired resistance to BRAF inhibitors." (PMID 32046241, 2020). "Although treatment with BRAF inhibitors or immune checkpoint inhibitors has provided promising results, most patients with advanced melanoma are resistant to these treatments and develop severe side effects." (PMID 31915016, 2020). "Inhibition of the MAPK pathway in both BRAF-mutant and wild-type melanoma cells resulted in increased tumor antigen expression and T-cell function." (PMID 32260561, 2020). "In the current study, we show that pyridinyl imidazole compounds are capable of simultaneously targeting the BRAF oncogene and mTORC1 signaling in human melanoma cells." (PMID 32531927, 2020). "In malignant cells isolated from BRAF mutant melanoma PDXs exposed to RAF/MEK inhibitors, varying combinations of distinct drug-tolerant transcriptional states were identified, which co-existed within MRDs from PDXs and biopsies of patients under therapy." (PMID 33322354, 2020). "Emerging evidence suggests that genome editing of BRAF V600E is possible and effectively induces the apoptosis of melanoma cells." (PMID 33330635, 2020). "With the activation of alternative isoforms of the RAF protein, BRAFV600E, melanoma treated with BRAF inhibitors can become resistant through flexible switching between RAF isoforms capable of ERK pathway signaling, increasing ARAF or CRAF expression." (PMID 32605090, 2020). "Initial in vitro and in vivo studies using BRAF-targeted therapies demonstrated increased melanoma antigen expression with tumor-infiltrating CD8+ T cells, and decreased levels of VEGF and immunosuppressive cytokines." (PMID 32260561, 2020). "In melanoma, longitudinal ctDNA assessment predicts overall survival of stage IV melanoma patients treated with either BRAF and MEK inhibitors or immunotherapy and the survival of patients with high-risk stage III resected melanoma." (PMID 32785074, 2020). "Together, our data suggest that inhibition of BET proteins improves the efficacy of BRAFi/MEKi in BRAF-mutant melanoma." (PMID 31932756, 2020). "An ongoing phase I trial is evaluating the safety and efficacy of phenformin in combination with dabrafenib and trametinib in BRAF-mutant melanoma (NCT03026517)." (PMID 33092283, 2020). "Conversely, miR-579-3p, melanoma tumor suppressor miR, is downregulated in vemurafenib-resistant cells and BRAF inhibitor-resistant patients." (PMID 32555626, 2020).
melanoma (continued). "Previously, we identified the plasma membrane Ca2+ pump isoform 4b (PMCA4b or ATP2B4) as a putative metastasis suppressor in BRAF mutant melanoma cells." (PMID 32414111, 2020). "Activation of YAP also plays a crucial role in the drug resistance of oesophageal cancer and in the BRAF inhibitor resistance of melanoma cells." (PMID 32281270, 2020). "Although BRAF inhibitors are used to treat melanoma, further options are needed due to treatment resistance and poor efficacy." (PMID 32962182, 2020). "For example, 18F-deoxyglucose positron emission tomography was applied for the detection of the early response to the B-Raf proto-oncogene, serine/threonine kinase (BRAF) inhibitor, vemurafenib, in BRAF-mutant melanoma patients." (PMID 33014847, 2020). "Although BRAF inhibitors can induce good responses in many patients with BRAF-mutant melanoma, in some cases, a reduction in effectiveness can be observed after 7–8 months of therapy." (PMID 32645969, 2020). "CCND1 alone can accelerate the resistance in BRAF-mutant melanoma and is intensified when there is both cyclin D1 overexpression along with a cyclin dependent kinase-4 (CDK4) mutation." (PMID 32092958, 2020). "Addition of inulin and mucin to the diet induces anti-tumor immune responses and inhibits subcutaneously implanted BRAF mutant melanoma in a syngeneic mouse model." (PMID 32560310, 2020). "Taken together, these data indicate that this combination was effective to kill a wide range of melanomas, however this is more potent in BRAF-WT samples than with BRAF-MUT samples." (PMID 32764384, 2020). "Patients with metastatic or unresectable melanoma treated with combination immune checkpoint blockade (Ipilimumab/Nivolumab) or BRAF/MEK inhibition demonstrate 5-year overall survival of 52% and 34%, respectively." (PMID 32764384, 2020). "Secondly, BRAF inhibitors increase T-cell infiltration into the tumour microenvironment of BRAF-mutant melanomas." (PMID 32645969, 2020). "BRAF inhibitors are ineffective in melanoma with wild-type BRAF because the homo- and heterodimers retain their signaling capacity, whereas these inhibitors block the action of monomeric BRAF." (PMID 33003483, 2020). "In BRAF inhibitor-resistant melanoma cells, a combination of MEK inhibitors with phosphatidylinositol 3-kinase (PI3K) or mechanistic target of rapamycin (mTOR) inhibitors can significantly decrease cancer cell survival." (PMID 32531927, 2020). "A number of studies demonstrated that resistance to BRAF and MEK inhibitors in malignant melanoma is associated with increased ROS levels." (PMID 32046099, 2020). "We demonstrate herein two facets of BRAF inhibition in melanoma cells: immunostimulatory activity due to decreased PD‐L1 transcription and translation, and immunosuppressive effect associated with Gal‐1 induction." (PMID 32330348, 2020). "It is well known that oncogenic BRAF can induce immunomodulation leading to an immune-suppressive phenotype that can facilitate the immune escape of melanoma cells." (PMID 32575838, 2020). "We, therefore, aimed to target autocrine Gal-1 signaling in BRAF-inhibitor-resistant melanoma cells from a therapeutic perspective." (PMID 32784465, 2020). "BRAF inhibition has been shown to increase melanoma cell immunogenicity, but these effects are transient and long‐term responses are uncommon." (PMID 32330348, 2020). "In summary, the triplet combination of dabrafenib, trametinib, and durvalumab is feasible in patients with BRAF-mutant advanced melanoma and induces robust and sustained immune modulation." (PMID 33288749, 2020). "Regarding these results, BPTES, a glutaminolysis inhibitor, was used on melanoma cells either sensitive or resistant to BRAF inhibitors." (PMID 32455924, 2020). "Based on these findings we decided to investigate the capability of SPV122 to potentiate target therapy for BRAF-mutant melanomas and to delay the emergence of drug resistance." (PMID 32933538, 2020).